SNCG (synuclein gamma)
Diseases named in the same sentence as SNCG in open-access papers:
SNCG is named in the same sentence as 32 diseases in open-access papers, as found by Europe PMC text mining. Sharing a sentence is not in itself a finding about the gene and the disease. The quoted sentences say what the papers report.
breast carcinoma (18 papers, 2008 to 2023). "High levels of SNCG (also called BCSG1 [breast cancer-specific gene 1]) have been identified in advanced breast carcinomas and associated with poor clinical outcome." (PMID 18928543, 2008). "In this regard, SNCG is overexpressed in human infiltrating breast carcinomas and promotes metastasis, while it is undetectable in normal and benign breast tissues." (PMID 37239828, 2023). "It is of interest to design the inhibitors for the breast cancer target synuclein gamma (SNCG) protein, using molecular docking-based virtual screening followed by molecular docking." (PMID 34221232, 2021). "Previous studies have shown that the expression of SNCG confers resistance to anti-microtubule drugs used in breast cancer treatment, such as nocodazole or taxol." (PMID 29937996, 2018). "In breast cancer cells, SNCG protein impairs cell cycle checkpoints, confers chemoresistance, and enhances metastasis in nude mice." (PMID 27595752, 2016). "Recently, γ-synuclein (SNCG), which is also known as breast cancer-specific gene-1, has been demonstrated to be an adverse and aggressive marker in breast cancer." (PMID 27551446, 2015). "Synuclein-gamma (SNCG) gene (also known as breast cancer-specific protein 1) was initially cloned from infiltrating breast carcinoma cells." (PMID 21448288, 2011). "Synuclein gamma (SNCG), initially identified as a breast cancer specific gene, is aberrantly expressed in many different malignant tumors but rarely expressed in matched nonneoplastic adjacent tissues." (PMID 20604972, 2010). "Besides this, ID4, SEMA3F, FOXD, KCNK5, WNK4 and ECM1 associate with chemoresistance origin and SOX5, ITM2A, SNCG, EPHA4, NTS, FGFR2 and ENPEP associate moreover with breast cancer tumorigenesis." (PMID 37239828, 2023). "In breast cancer cells, SNCG interacts with phospholipase Cβ2 to modulate G protein activation and it also has the potential to stimulate the ER pathway, which may increase cell malignancy." (PMID 27595752, 2016). "Next, we investigated whether SNCG, known to be a secretory molecule, is released from irradiated breast cancer cells." (PMID 27551446, 2015). "In our previous study, SNCG was significantly upregulated in irradiated human breast cancer cells." (PMID 27551446, 2015). "In addition to its involvement in the checkpoint complex, SNCG has also been shown to stimulate the ligand-dependent transcriptional activity of ER in breast cancer cells." (PMID 23599792, 2013). "The study by He and Wang (2015) found higher expression levels of lncRNA-AK058003 that promoted breast cancer cell proliferation and EMT via the regulation of SNCG (Synuclein Gamma) expression." (PMID 36685962, 2022). "Synuclein-γ (SNCG) was first identified as breast cancer–specific gene 1 (BCSG1), and was isolated from cDNA libraries of breast carcinoma in the 1990s." (PMID 27595752, 2016). "Since SNCG was first observed to be overexpressed in advanced breast carcinoma, but not in normal or benign breast tissue, it was previously named breast cancer specific gene 1 (BCSG1)." (PMID 23599792, 2013). "SNCG has been described as playing a role in regulating resistance to chemotherapeutic agents in breast cancer, but whether SNCG modulates radiosensitivity of breast cancer cells is not known." (PMID 29937996, 2018). "Numerous reports have also suggested that SNCG is not expressed in normal and benign breast tissues but expressed abnormally in a high percentage of advanced and metastatic cancer and stimulates hormone-dependent growth of breast cancer cells both in vitro and in nude mice." (PMID 34221232, 2021).
ovarian carcinoma (6 papers, 2015 to 2023). A malignant neoplasm originating from the surface ovarian epithelium. "Emerging evidence has indicated that SNCG is highly expressed and tightly associates with tumor progression and metastasis, including gynecologic processes (endometriosis, cervical, endometrial and ovarian cancers)." (PMID 32381034, 2020). "Promoter hypomethylation induced upregulation of other cancer-associated genes in ovarian cancer includes maspin (SERPINB5), MCJ, and SNCG (synucelin-γ), which encodes an activator of the MAPK and Elk-1 signaling cascades." (PMID 31608277, 2019). "Among such targets, synuclein gamma (SNCG) was proposed as a potential target in ovarian cancer therapy." (PMID 27809878, 2016). "Through activating the PI3K/AKT signaling pathway, SNCG can promote ovarian cancer cell metastasis." (PMID 36996495, 2023).
gastric cancer (5 papers, 2016 to 2024). A primary or metastatic malignant neoplasm involving the stomach. "SNCG exhibits high expression levels in the gastric juice and serum of gastric cancer patients and contributes to the progression of the disease." (PMID 39044041, 2024). "Previous studies have revealed that the SNCG acts as an oncogene in many cancers, including liver cancer, esophageal cancer, gastric cancer, colon cancer and cervical cancer." (PMID 28035067, 2017). "In gastric cancers, the mRNA of a proto-oncogene, synuclein gamma (SNCG), is highly expressed due to its CpG demethylation whereas its expression is not detected in non-neoplastic gastric mucosal tissues." (PMID 26861406, 2016). "Notably, in gastric cancer cells, lncRNA-AK058003, located upstream of synuclein gamma (SNCG, a metastasis-associated protein), is robustly upregulated by hypoxia and regulates SNCG expression in cis by demethylating CpG islands within its promoter, thereby promoting hypoxia-induced metastasis." (PMID 28789687, 2017).
cervical cancer (3 papers, 2017 to 2024). A primary or metastatic malignant neoplasm involving the cervix. "SNCG, primarily expressed in neural tissues, is reported to upregulate in cancer tissues such as breast, ovary, colon, liver, and cervical cancer." (PMID 38962317, 2024). "Taken together, our research showed that SNCG might be an oncogene which promoted cervical cancer tumorigenesis in vitro and in vivo." (PMID 31333726, 2019).
glaucoma (3 papers, 2020 to 2025). Increased pressure in the eyeball due to obstruction of the outflow of aqueous humor. "A common hallmark of glaucoma is the loss of retinal ganglion cells (RGCs), while γ-synuclein (SNCG) is highly expressed in somatic cells and synapses in RGCs, and PFDN2 can be a candidate upstream regulator to identify SNCG expression." (PMID 32699605, 2020).
Obesity (3 papers, 2012 to 2024). Accumulation of substantial excess body fat. "SNCG (synuclein gamma) has recently been termed an adipocyte-neuron gene that is coordinately expressed with leptin in human obesity and might promote adipocyte differentiation." (PMID 22369239, 2012).
depression (2 papers, 2012 to 2025). "Apart from its well-known role in the development of neurodegenerative diseases, SNCG has also been implicated in depression, dopamine release and as an interacting partner of the dopamine transporter in rats." (PMID 22369239, 2012). "One overlapping protein, Sncg (synuclein-gamma), a member of the synuclein family, is suggested to be involved in neurodegenerative pathology in mice and in the pathophysiology of depression in rat models." (PMID 39623245, 2025).
hepatocellular carcinoma (2 papers, 2021 to 2023). A malignant tumor that arises from hepatocytes. "The neuronal protein, synuclein-gamma (SNCG), is highly expressed in advanced hepatocellular carcinomas, and SNCG gene activation via demethylation in tumor tissue of HCC is not limited to HBV and HCV infection." (PMID 34336665, 2021). "The neuronal protein, synuclein gamma (SNCG), is highly expressed in advanced hepatocellular carcinomas and demethylation in tumor tissue of HBV and HCV-related HCC." (PMID 37726886, 2023).
oral cancer (2 papers, 2020). "Thus, nicotine-induced oral cancer malignancy may be caused by the upregulation of SNCG expression, and may lead to ECM degradation, which contributes to malignant behaviors, such as invasion and migration." (PMID 32669976, 2020). "Therefore, the present study investigated the potential involvement of SNCG in mediating nicotine-induced oral cancer malignancy." (PMID 32669976, 2020).
benign breast diseases (1 paper, 2022). "In the current study, MALAT1 was down-regulated but SNCG and HOTAIR were significantly up-regulated in patients with benign breast diseases." (PMID 36376369, 2022).
bladder cancer (1 paper, 2016). "Gamma-synuclein (SNCG) is secreted from tumor cells and elevated in the urine of bladder cancer (BCa) patients, however, the diagnostic and prognostic values of urine SNCG for BCa remain unknown." (PMID 27223068, 2016).
glioma (1 paper, 2021). A benign or malignant brain and spinal cord tumor that arises from glial cells (astrocytes, oligodendrocytes, ependymal cells). "In addition, we also found that SNCG and CDK6 are related to prognosis of glioma; SNCG to dendritic cells; and CDK6 to immunity." (PMID 34615480, 2021). "Thus, we developed a prognostic prediction model for glioma patients using four mRNAs, namely, SNCG, PGD, CDK6, and GCC1." (PMID 34615480, 2021).
metastatic cancer (1 paper, 2018). A carcinoma which has spread from the original site of growth to another anatomic site. "Gamma-synuclein (SNCG) is overexpressed in a variety of invasive and metastatic cancer." (PMID 29795373, 2018).
oral squamous cell carcinoma (1 paper, 2020). "The mechanisms of neuronal protein γ-synuclein (SNCG) in the malignancy of oral squamous cell carcinoma (OSCC) are not clear." (PMID 32669976, 2020).
prostate carcinoma (1 paper, 2012). A carcinoma that arises from epithelial cells of the prostate gland. "Since SNCG is expressed at high levels in androgen-dependent and at low levels in androgen-independent prostate cancer cells, we raised the question whether SNCG is involved in mediating hormone-dependent tumorigenicity." (PMID 23231703, 2012). "Gamma-synuclein (SNCG) has previously been demonstrated to be significantly correlated with metastatic malignancies; however, in-depth investigation of SNCG in prostate cancer is still lacking." (PMID 23231703, 2012).
scrapie (1 paper, 2022). A fatal disease of the nervous system in sheep and goats, characterized by pruritus, debility, and locomotor incoordination. "Of all the selected genes, significant changes between the control and scrapie animals were found in the expression of five genes: PCDH19, SNCG, WDR45B, PEX1, and CABIN1." (PMID 35252421, 2022). "We identified many DMRs between the control and scrapie animals, some of them belonging to genes with possible neuroprotective roles against neurodegeneration (SNCG and WDR45B) and to genes that may facilitate or contribute to scrapie disease progression (PCDH19, PEX1, and CABIN1)." (PMID 35252421, 2022).
cancer (28 papers, 2010 to 2025). A tumor composed of atypical neoplastic, often pleomorphic cells that invade other tissues. "The loss of epigenetic control of SNCG (synuclein-gamma) seems to be a molecular indicator of metastasis in a wide range of human cancers, including BRCA and PRAD." (PMID 31238876, 2019). "Some studies in other cancers reported SNCG is implicated in regulation of key steps of cellular proliferation, invasion and metastasis as well as survival." (PMID 23231703, 2012). "Synuclein-γ (SNCG) is the third member of the synuclein family, which is strongly associated with malignant progression and distant metastasis in different types of cancer." (PMID 31333726, 2019). "Furthermore, abundant expression of SNCG has also been associated with several other types of cancer, including ovary, cervical, prostate, pancreatic, colon and lung." (PMID 29937996, 2018). "Gamma synuclein (SNCG) is a neuronal protein that is also aberrantly overexpressed in various types of human cancer." (PMID 35637967, 2022). "Synuclein-γ (SNCG) and Snai1 play an important role in the occurrence and development of different types of malignant tumors." (PMID 35434126, 2022). "Gamma‐synuclein (SNCG) promotes invasive behavior and is reportedly a prognostic factor in a range of cancers." (PMID 34245137, 2021). "SNCG protein is abnormally expressed in a high percentage in various malignant tumor tissues including liver, breast, ovarian, prostate and colon cancer, while it is rarely expressed in tumor-matched non-neoplastic adjacent tissues." (PMID 31333726, 2019). "The SNCG-BubR1 interaction can prevent the activation of SAC (spindle assembly checkpoint) caused by microtubules inhibitors, and as a result, allowing cancer cells to progress into the cell cycle and escape apoptosis." (PMID 29937996, 2018). "Functionally, SNCG acts as a chaperone protein and was found highly expressed in multiple cancer types such as advanced stage breast and ovarian cancers." (PMID 26265438, 2015). "γ-Synuclein (SNCG) has reported as a critical player in cancer metastasis." (PMID 32381034, 2020). "SNCG promotes cancer metastasis and cancer cell survival under stresses." (PMID 29795373, 2018). "Thus, synuclein-γ (SNCG) abnormal expression has been described in a wide range of human cancer such as endometrial, bladder, prostate, ovarian, gastric, liver, lung, colon, and breast." (PMID 29937996, 2018). "Synuclein gamma (SNCG) is under consideration as a potential biomarker in cancer biology." (PMID 26265438, 2015). "Therefore, our data suggest that SNCG may have important roles in promoting the malignant aspects of BTC, as it does in other types of cancers; however, the detailed functions of SNCG likely differ depending on the cancer type and localization." (PMID 34245137, 2021). "Gamma-Synuclein (SNCG), the third member of the neuronal protein synuclein family, participates in the pathogenesis of several types of cancer and some neurodegenerative diseases." (PMID 29903032, 2018). "The highly abundant protein in HGSC compared to EC, SNCG, is a suggested therapeutic target in other cancers but has not been identified for EOC to date." (PMID 40778374, 2025). "Gamma synuclein (SNCG), a neuronal protein, is overexpressed in different types of cancer." (PMID 37248432, 2023). "For some cancer cells, positive SNCG staining was also observed in nucleus and membrane, suggesting that SNCG is not an exclusively cytoplasmic protein." (PMID 20604972, 2010). "BUB1B is also a cellular target of synuclein-gamma (SNCG, also known as breast cancer specific gene 1), with which it may interact to inactivate the mitotic checkpoint, and contribute to resistance of beast cancer cells to microtubule inhibitors." (PMID 21785684, 2011).
tumor (24 papers, 2008 to 2025). "However, whether this radiation-induced expression of SNCG might be implicated in the protection of the tumor cells themselves remains to be determined." (PMID 29937996, 2018). "In contrast, the lower expression levels of APOC3 and SNCG in tumor, together with their protective roles in the prognostic signature, have further revealed their potential suppressor functions in GC." (PMID 37100457, 2023). "SNCG shares 60% sequence homology with alpha‐synuclein and is also mainly expressed in presynaptic nerve terminals in normal tissues; however, SNCG is also characteristically expressed in malignant tumor cells." (PMID 34245137, 2021). "Recent studies show the overexpression of SNCG is tightly involved in the multiple complex mechanisms mediating tumor progression." (PMID 32381034, 2020). "In the present study, we demonstrated that SNCG, as a secreted protein, also controlled secretion of many proteins in the tumor microenvironment, including ECM proteins such as fibronectin, vitronectin, the MMPs like MMP-2 and MMP-24." (PMID 29903032, 2018). "SNCG is a soluble protein predominantly distributed in the cytosol of tumor cells and functions both intra- and extra-cellularly, just like alpha-synuclein (SNCA), another member of synuclein family." (PMID 29903032, 2018). "SNCG is overexpressed in various tumor tissues and predict adverse outcomes in breast, colon, and pancreatic cancer patients." (PMID 27223068, 2016). "Others genes in this cluster were targets of estrogen action (e.g. T-type calcium channel subunit; CACNA1G), capable of binding estrogen receptor alpha (FASN, SNCG), or involved in tumor suppression (PRKCD, RASL11A)." (PMID 18941504, 2008). "However, the mechanism of SNCG regulates protein secretion from tumor cells still awaits further characterization." (PMID 29903032, 2018). "We found SNCG was not expressed in benign epithelium cells, but aberrantly expressed in advanced malignant states, suggesting that SNCG may be a tumor-oriented chaperone." (PMID 23231703, 2012). "We then investigated the expression of ESR1/ERα and that of the five following top-ranked genes (MET, FOS, SNCG, IGFBP4, and BCL2) by RTQ-PCR on the initial set of 18 tumor samples (eight control and 10 TF)." (PMID 18928543, 2008). "In addition to ESR1/ERα, the top-ranked genes selected by statistical cross-analyses were MET, FOS, SNCG, IGFBP4, and BCL2, which were subsequently validated in a larger set of tumor samples (from 17 control patients and 18 TF patients)." (PMID 18928543, 2008). "However, SNCG is clearly not involved in neurodegenerative diseases but is primarily involved in neoplastic diseases." (PMID 32669976, 2020).
neurodegenerative disease (4 papers, 2012 to 2023). A disorder of the central nervous system characterized by gradual and progressive loss of neural tissue and neurologic function. "γ‐synuclein (SNCG), together with α‐ and β‐synuclein, constitutes the highly conserved synuclein family and participates in development of malignant and neurodegenerative diseases." (PMID 36658726, 2023).
SNCG also shares sentences with these, for which no sentence is quoted: colon cancer (2 papers); breast tumor (1); colon adenocarcinoma (1); colorectal cancer (1); Creutzfeldt Jacob disease (1); endometrial cancer (1); endometriosis (1); esophageal cancer (1); liver cancer (1); melanoma (1); pancreatic cancer (1); synucleinopathies (1); urothelial carcinoma (1).